SIRT3 (sirtuin 3)
Diseases named in the same sentence as SIRT3 in open-access papers (continued):
Sharing a sentence is not in itself a finding about the gene and the disease.
metabolic disease (continued). "By targeting SIRT3 activity, it may be possible to enhance oocyte quality, extend reproductive longevity, and mitigate the detrimental effects of age and metabolic disorders on fertility." (PMID 39329773, 2024). "Thus, SIRT3 protects human from metabolic diseases, and SIRT3 modulators will shine in the prevention and early treatment of metabolic diseases." (PMID 32724473, 2020). "In short, SIRT3 can protect the kidney from metabolic disease." (PMID 32724473, 2020). "Recent evidence implicates the critical role of Sirtuin 3 (SIRT3) in the development of many metabolic diseases, but the contribution of SIRT3 to vascular homeostasis remains largely unknown." (PMID 27000941, 2016). "Moreover, HFD downregulates SIRT3 to inactivate the ERK-CREB pathway to trigger metabolic diseases." (PMID 36678226, 2023). "SIRT3 also plays a role in adipose tissue inflammation, through its function in macrophages and ameliorating inflammatory crosstalk between macrophages and adipocytes; thus, modulation of SIRT3 may be beneficial for the treatment of adipose tissue inflammation-related metabolic disorders." (PMID 33806509, 2021). "Importantly, LCar and LW6 administration could improve iBAT thermogenesis of aging mice via regulating ACar metabolism, suggesting that the Sirt3/HIF1α axis and ACar metabolism in BACs might be a potential therapeutic target for aging related metabolic disorder." (PMID 39348266, 2024). "The investigated parameters related to metabolic disorders included sirtuin 1 (SIRT-1), sirtuin 3 (SIRT-3), sirtuin 6 (SIRT-6), irisin (IRS), myostatin (MSTN), peptide YY (PYY), glucagon-like peptide 1 (GLP-1), and dipeptidyl peptidase 4 (DPP-4)." (PMID 39124846, 2024). "Our previous study confirmed that SIRT3 is a functional target of DHM for its prevention and treatment of metabolic diseases." (PMID 36678226, 2023).
infection (34 papers, 2011 to 2025). The state of being infected such as from the introduction of a foreign agent such as serum, vaccine, antigenic substance or organism. "Altogether, our results revealed that SIRT3 displays infection-induced changes in its association with the fusion factor OPA1, which are temporally dynamic and that match K834 acetylation levels on this substrate." (PMID 33857259, 2021). "SIRT3 deficiency led to increased bacterial loads, histopathological, and mitochondrial damage, and pathological inflammation during Mabc infection." (PMID 32835604, 2020). "SIRT3 deficiency has been reported to promote chronic inflammation-related disorders, but whether SIRT3 impacts on innate immune responses and host defenses against infections remains essentially unknown." (PMID 28634345, 2017). "We knocked down SIRT3 by infection with lentivirus-shSIRT3 and found that the reduction in SIRT3 expression significantly aggravated FFA-induced lipid accumulation but abolished the ameliorative effects of HINT2 overexpression in HepG2 cells." (PMID 40307568, 2025). "(D, E) Lactate estimation assay of S. Typhimurium-infected RAW 264.7 macrophages upon Sirt1 (D) or Sirt3 (E) knockdown condition at 16 hr post-infection." (PMID 39693143, 2024). "Knockdown of Sirt1 or Sirt3 in infected RAW 264.7 macrophages resulted in a reduction in anti-inflammatory CD206 surface marker expression at 16 hr post-infection." (PMID 39693143, 2024). "Inhibition of both SIRT1 and SIRT3 increased production of pro-inflammatory cytokine IL-6 significantly at 2 hr and 20 hr post-infection." (PMID 39693143, 2024). "This altered host metabolism upon Sirt1 and Sirt3 knockdown condition influences the outcome of infection by regulating the intracellular bacterial metabolism, which shows reduced bacterial glycolysis and increased FAO." (PMID 39693143, 2024). "On the other hand, the Sirt3 transcript levels remained elevated at all time points with respect to uninfected control with a marked increment at 16 hr time point post-infection, which subsided at 20 hr post-infection." (PMID 39693143, 2024). "In line with the confocal microscopy data, SIRT3 immunoblotting data shows an increased protein expression profile at 6 hr and 16 hr post-infection." (PMID 39693143, 2024). "Upon infection of RAW 264.7 murine macrophages with wildtype S. Typhimurium strain 14028S, we observed an increased expression level of Sirt1 and Sirt3 at initial and middle phases of infection, precisely at 2 hr and 6 hr post-infection through qPCR." (PMID 39693143, 2024). "Immunoblotting revealed increased protein expression of both SIRT1 and SIRT3 at 2 hr post-infection in comparison to the uninfected control." (PMID 39693143, 2024). "Following that, we used oxidation-sensitive dyes, DCFH-DA and MitoSOX, to visualize the oxidative fluorescent signals with a fluorescence microscope to examine the role of intracellular ROS in osteoclast precursors with SIRT3 siRNAs or vehicle infection." (PMID 38246920, 2024). "(J) qPCR-mediated expression of Sirt3 in RAW 264.7 macrophages upon infection with wildtype S. Typhimurium or SPI-1 (∆invC) or SPI-2 (∆ssaV and ∆steE) mutants of S. Typhimurium." (PMID 39693143, 2024). "Several reports indicate the role of SIRT1 and SIRT3 in the modulation of host immune responses pertaining to infection scenarios." (PMID 39693143, 2024). "Results depicted significant enhancement in the production of ROS at 16 hr post-infection upon knockdown of Sirt1 or Sirt3 in comparison to untransfected or scrambled control." (PMID 39693143, 2024). "(C) Quantitative representation of flow cytometric analysis of M2 surface marker CD206 in STM-infected Sirt1 or Sirt3 knockdown RAW 264.7 macrophages in comparison to the scrambled control at the indicated time post-infection." (PMID 39693143, 2024). "(G) Representative confocal images of RAW 264.7 macrophages exhibiting SIRT3 expression upon S. Typhimurium infection at indicated time points post-infection." (PMID 39693143, 2024).
infection (continued). "(F) Immunoblotting of host glycolytic (PGK), TCA cycle (PDHA1), and fatty acid oxidation (HADHA, ACOX-1) proteins under Sirt1 and Sirt3 knockdown condition of S. Typhimurium-infected RAW 264.7 macrophages at 16 hr post-infection." (PMID 39693143, 2024). "(B) In vivo organ burden of STM upon SIRT1 or SIRT3 inhibition in C57BL/6 mice on fifth day post- infection under specified dosage of inhibitor treatment." (PMID 39693143, 2024). "In confocal laser scanning microscopy (CSLM) studies, we observed a similar increase in SIRT1 and SIRT3 expression at 6 hr post-infection within the infected macrophages RAW 264.7 macrophages." (PMID 39693143, 2024). "(D) Representation of splenic length of STM- infected spleen tissue harvested from C57BL/6 mice (males) on fifth day post- infection upon SIRT1 or SIRT3 inhibition at 1 mg/kg dosage." (PMID 39693143, 2024). "(E) Bacterial load in blood at different days post- infection upon SIRT1 or SIRT3 inhibition at 1 mg/kg dosage in C57BL/6 mice (males)." (PMID 39693143, 2024). "PRDX3 decreased sirtuin-3 (SIRT3) expression during infection and increased acetylation in Caco-2 cells." (PMID 38438362, 2024). "In the wildtype C57BL/6 mice treated with SIRT3 inhibitor 3TYP showed heightened bacterial burden in blood at 5th day post-infection in comparison to the vehicle control." (PMID 39693143, 2024). "Upon detection of extracellular ROS generation through phenol red hydrogen peroxidase assay, we detected higher ROS generation upon Sirt3 KD at 6 hr post-infection and greater ROS production at 16 hr and 20 hr time points in Sirt1 knockdown macrophages." (PMID 39693143, 2024). "(C) In vivo organ burden of STM upon Sirt1 or Sirt3 adenovirus-mediated in vivo knockdown in C57BL/6 mice on fifth day post-infection." (PMID 39693143, 2024). "(G) Serum IL- 6 levels of STM- infected C57BL/6 WT mice (males) mice treated with SIRT1(EX- 527) or SIRT3 (3TYP) inhibitors or SRT1720 (SIRT1 activator) at 1 mg/kg dosage on fifth day post- infection." (PMID 39693143, 2024). "(F) Bacterial load in blood on fifth day post- infection upon SIRT1 or SIRT3 inhibition at 1 mg/kg dosage in C57BL/6 WT mice (males) and cybb-/- (males) mice." (PMID 39693143, 2024). "Second, it is possible that SIRT3 basilar expression is attenuated by various infections (as we have shown it is during P. aeruginosa pneumonia) and therefore, unable to contribute significantly to the host response." (PMID 35215060, 2022). "Our data suggest that therapies targeting the PGC-1α-SIRT3 mitochondrial pathway can attenuate potentially damaging inflammasome activation and augment the host response to infection." (PMID 35215060, 2022). "More broadly, the large number of mitochondrial SIRT3 substrates and their overall increase in acetylation levels during infection suggest a link between the global mitochondrion acetylation status and its structure." (PMID 33857259, 2021). "We establish that SIRT3 deacetylase activity is necessary for suppressing virus production, and that SIRT3 maintains mitochondrial pH and membrane potential during infection." (PMID 33857259, 2021). "Compared with the Ad-GFP group, Ad-SIRT3 infection at MOI 50 and MOI 100 significantly increased the mRNA abundance of MTP (p < 0.05)." (PMID 34208809, 2021). "We injected WT and SIRT3-/- mice intraperitoneally with S. typhimurium and monitored the IL-1β levels in the serum of these mice 6 h after infection." (PMID 33664876, 2021). "This is in agreement with our observations that SIRT3 acts in antiviral response early in infection and that its deacetylase activity contributes to this function." (PMID 33857259, 2021). "The mRNA abundance of ApoB100 displayed a dose-dependent manner upon Ad-SIRT3 infection with MOI 100 the highest (p < 0.001)." (PMID 34208809, 2021). "Together, these data supported an infection-induced metabolic shift toward glycolysis in primary and J2 macrophages due, at least in part, to reduced SIRT3 expression." (PMID 33531400, 2021).
infection (continued). "To determine when during infection SIRT3 exerts its antiviral function, we assessed markers of different stages of HCMV replication." (PMID 33857259, 2021). "Infection of Sirt3−/− BMDM resulted in a further 1.5-fold increase of ROS compared to infected WT cells." (PMID 33531400, 2021). "The breadth of the identified interactions and their dynamic nature underscores the versatility of SIRT3 in regulating multiple mitochondrial metabolic pathways during infection." (PMID 33857259, 2021). "This decreased interaction with SIRT3 aligned with an increase in ACAA2 acetylation levels during infection." (PMID 33857259, 2021). "Metabolic changes have been reported to occur at earlier infection time points than our 72 hpi SIRT3 interaction study, with increased flux through glycolysis and elevated fatty acid synthesis observed already by 48 hpi." (PMID 33857259, 2021). "Ad-SIRT3 infection in response to 1 mM NEFA incubation significantly increased the mRNA abundance of MTP, ApoB100, and ApoE, and raised VLDL contents in the supernatants." (PMID 34208809, 2021). "To this end, we started by determining the changes in SIRT3 interactions at a late stage of infection, when mitochondrial integrity is already disrupted and changes in cellular metabolism were reported as prevalent." (PMID 33857259, 2021). "We show that the SIRT3 activity helps to maintain the mitochondrial membrane potential and the mitochondrial pH during infection." (PMID 33857259, 2021). "The fact that SIRT3 maintains the MMP and pH during infection also guides us to ask how SIRT3 modulates mitochondrial metabolism during infection." (PMID 33857259, 2021). "We find that OPA1 knockdown and over-expression have an impact on mitochondrial morphology and HCMV viral protein levels at 24 hpi, suggesting that the SIRT3 substrate OPA1 exerts a virus restriction function early in infection." (PMID 33857259, 2021). "Bacterial burden was also greater in lungs of LysMcreSirt3L2/L2 mice, demonstrating the importance of macrophage-specific SIRT3 after infection." (PMID 33531400, 2021). "The infection-induced increase in acetylation was also evident on SIRT3 substrates, with a marked global upregulation by 72 hpi." (PMID 33857259, 2021). "Our data suggest that elevated mtROS after infection results from downregulation of SIRT3 and consequently NDUFS7 and NDUFV3." (PMID 33531400, 2021). "Along with downregulation of TCA and ETC components, we observed SIRT3-dependent upregulation of Hk2 and Glut1 and increased lactate secretion following infection, indicating a shift toward glycolysis." (PMID 33531400, 2021). "In our study, a low-dose aerosol infection with M. tuberculosis Erdman also increased the mortality of Sirt3−/− mice compared to WT controls." (PMID 33531400, 2021). "The intracellular survival assays revealed that the SIRT3 KO BMDMs had significantly higher intracellular Mabc-S (multiplicity of infection [MOI] = 1 and 3) compared to the SIRT3 WT BMDMs." (PMID 32835604, 2020). "When compared with SIRT3 WT BMDMs or PMs, SIRT3 KO BMDMs or PMs showed a significantly increased mRNA levels of Tnf, Il6, and Cxcl2 after infection with Mabc-R." (PMID 32835604, 2020). "When SIRT3 WT mice were intranasally infected with Mabc-R, SIRT3 protein levels were significantly reduced (~ 2 fold) at 1 day post-infection (dpi) in the lung tissues from mice." (PMID 32835604, 2020). "In vivo bacterial loads in the lungs were significantly higher in SIRT3 KO mice than in SIRT3 WT mice after infection with Mabc-R or Mabc-S." (PMID 32835604, 2020). "Mabc-R-mediated mRNA generation of Tnf, Il6, and Cxcl2 was significantly increased in BMDMs from SIRT3 KO mice compared to SIRT3 WT mice after infection in a time-dependent manner." (PMID 32835604, 2020).
infection (continued). "Going well along with an improved response to infection, SIRT3/5−/− mice had significantly higher blood concentrations of TNF at day 1 (P = 0.001), TNF and IL-1β at day 2 (P = 0.004 and 0.03) and KC/CXCL1 at day 3 (P = 0.05)." (PMID 31632409, 2019). "Two days post-infection, bacteremia was low but slightly higher in SIRT3−/− mice (median: 7.5 × 102 CFU/ml vs 1.1 × 103 CFU/ml; P = 0.02)." (PMID 28634345, 2017). "Infection with H. pylori CagA induced downregulation of SIRT3 protein in mitochondria, stimulated ROS production, and elicited HIF-1α stabilization with increased transcriptional activity, similar to that observed during hypoxia." (PMID 29108235, 2017). "This study also found that downregulation of CypD by siRNA infection and SIRT3 overexpression attenuated apoptotic and necrotic types of cell death, and had positive effects in the hippocampus." (PMID 28236057, 2017). "Overexpression of SIRT3 by Lv-SIRT3 infection abolished the palmitate-induced inhibition on both insulin signaling and insulin-stimulated NO production, suggesting that SIRT3 overexpression improves insulin resistance induced by palmitate in endothelial cells." (PMID 27000941, 2016). "siRNA-mediated knockdown of SIRT3 resulted in a significant elevation in mitochondrial O2•− generation while overexpression of SIRT3 by Lv-SIRT3 infection significantly inhibited mitochondrial O2•− increase induced by palmitate in endothelial cells." (PMID 27000941, 2016). "Lower protein levels of SIRT3 were detected after Ad-SIRT3SF infection than after Ad-SIRT3LF infection, even though the transcription levels were similar (data not shown)." (PMID 25915406, 2015). "In the cells pretreated with Ad.SIRT3 infection compared with the controls, the cholesterol and triglyceride accumulation was reduced 40% and 50% respectively." (PMID 25748450, 2015). "In these tissue culture experiments, co-infection of lenti-MnSOD not only decreased mitochondrial superoxide levels but also prevented immortalization of Sirt3−/− MEFs by a single oncogene." (PMID 22016654, 2011). "In this study, the expression of Sirt3 in cementoblasts was found to be increased during cementoblast mineralisation and cementum development, while it decreased gradually under P.g. infection in a multiplicity of infection‐dependent manner." (PMID 40068967, 2025). "However, at the protein level, only SPI-2 mutant infection resulted in a predominant decline in SIRT3 expression and a mild reduction in SIRT1 expression." (PMID 39693143, 2024). "Salmonella modulates the expression of SIRT1 and SIRT3 along its course of infection." (PMID 39693143, 2024). "Lactate estimation assay in Sirt1 and Sirt3 knockdown condition revealed enhanced lactate production at 16 hr post-infection in comparison to the scrambled control, which further authenticates the increased host glycolysis upon Sirt1 and Sirt3 knockdown scenario." (PMID 39693143, 2024). "However, our in vivo findings in the murine model of infection show increased bacterial burden upon SIRT1 or SIRT3 inhibition." (PMID 39693143, 2024). "Moreover, there was only a significant reduction in anti-inflammatory IL-10 production upon Sirt1 and Sirt3 knockdown at 2 hr and 20 hr post-infection." (PMID 39693143, 2024). "The function of SIRT3 in infection scenario has been explored quite recently." (PMID 39693143, 2024). "Then, we overexpressed SIRT3 by lentivirus infection on SW620 and HT29 cells." (PMID 34747319, 2022). "SIRT3 siRNA-mediated knockdown (validated in S2C Fig) resulted in decreased mitochondrial pH in uninfected cells, and this decrease was exacerbated during infection." (PMID 33857259, 2021). "As the proton gradient accounts for a portion of MMP, we hypothesized that the mitochondrial pH is also affected by infection and modulated by SIRT3." (PMID 33857259, 2021).